PINK1 (PTEN induced kinase 1)
Diseases named in the same sentence as PINK1 in open-access papers (continued):
Sharing a sentence is not in itself a finding about the gene and the disease.
lung carcinoma (continued). "In summary, circRREB1 may regulate mitochondrial function through PINK1/Parkin-mediated mitophagy and thereby promote the development of lung cancer." (PMID 40653497, 2025). "Silencing PINK1 can inhibit the proliferation of lung cancer cells and disrupt their cell cycle." (PMID 38155968, 2023). "In addition, these findings suggest that PINK1 induces lung cancer cell resistance through the NF-κB pathway." (PMID 36909198, 2023). "For example, PINK1 overexpression is linked to a poor response to chemotherapy and a poor prognosis in patients with esophageal squamous cell carcinoma treated with neoadjuvant chemotherapy, while silencing PINK1 inhibits lung cancer cell growth and migration while also inducing cell death." (PMID 35326612, 2022). "And the further studies indicated compounds 6 and 7 could trigger autophagy, PINK1/Parkin-mediated mitophagy in cancer cell lines, and also suppress lung cancer A549 cells metastasis targeting Akt and cofilin signaling pathways." (PMID 32016770, 2020). "Silencing of PINK1 inhibited the proliferation of lung cancer cells and blocked the cell cycle." (PMID 33244455, 2020). "Collectively, our findings provide information helpful for clarifying the coregulatory mechanism of MFN2 and UCP4, which may regulate intercellular calcium homeostasis through PINK1‐mediated mitophagy or ER–mitochondria tethering and thereby affect the biological properties of lung cancer cells." (PMID 36877954, 2023). "PINK1 may be involved in some lung diseases, including lung cancer." (PMID 33066407, 2020). "In addition, these compounds could induce autophagy and PINK1/Parkin-mediated mitophagy in cancer cell lines, as well as suppress lung cancer A549 cells metastasis in vitro." (PMID 32016770, 2020). "Our pan-cancer analysis revealed minimal differences between PINK1 and PRKN2, suggesting that they fulfil similar functions in tumors like lung cancer." (PMID 39859167, 2025). "PINK1 and BNIP3 are both upregulated in lung cancer, while in ovarian cancer, PINK1 is downregulated, and BNIP3 is upregulated." (PMID 39765891, 2024). "To further explore the underlying mechanism involved in CVB-D-induced mitophagy, we first detected the expression of parkin/Pink1 and BNIP3/BNIP3L in lung cancer cells upon CVB-D treatment." (PMID 34072333, 2021). "We further explored the correlation between PINK1 expression and several clinicopathological characteristics in LIHC and lung cancer." (PMID 33244455, 2020). "In summary, circRREB1 may increase the expression level of PINK1 by targeting HSPA8, thereby inducing mitophagy and ultimately promoting the development of lung cancer." (PMID 40653497, 2025). "However, better survival was mostly noted when PINK1 and PRKN2 were downregulated, except in lung cancer." (PMID 39859167, 2025). "We designed rescue experiments to explore whether circRREB1 regulates PINK1 protein expression through HSPA8, which in turn regulates mitophagy to promote lung cancer development." (PMID 40653497, 2025). "The results showed that parkin exhibits decreased expression in all lung cancer cells, and Pink1 showed a decreased expression in 95-D cells, but no obvious change was detected in A549 and H446 cells." (PMID 34072333, 2021).
Sepsis (32 papers, 2020 to 2025). Sepsis is defined as life-threatening organ dysfunction caused by a dysregulated host response to infection. "PINK1- and Parkin-deficient mice are more sensitive to polymicrobial sepsis-induced multiple organ failure and death." (PMID 40599023, 2025). "PINK1 plays a pivotal role in sustaining mitochondrial homeostasis and mitigating sepsis-associated injury." (PMID 40766066, 2025). "In our study, we elucidated the effect of PINK1 on DC function during sepsis and its underlying mechanism of action." (PMID 36809929, 2023). "Previous research have shown that PINK1 deficiency contributes to the severity of organ dysfunction during sepsis." (PMID 36809929, 2023). "We found that expression of PINK1 decreased in mouse hearts during sepsis, which caused cardiomyocyte mitochondrial Ca2+ efflux disorder, mitochondrial calcium overload, and cardiomyocyte injury." (PMID 33957982, 2021). "Moreover, PINK1 deficiency contributes to the severity of multiple organ injury during sepsis and increases the mortality rate of CLP mice." (PMID 36809929, 2023). "In murine hearts during sepsis, reduced PINK1 expression impairs mitochondrial Ca2+ efflux in cardiac cells, resulting in mitochondrial calcium overload and cardiomyocyte injury." (PMID 40766066, 2025). "In conclusion, we demonstrated that CDDO-Im alleviates sepsis-related ARDS through the activation of PINK1/Parkin-mediated mitophagy to inhibit AM pyroptosis and HMGB1 release bothin vivo andin vitro via the Nrf2 pathway." (PMID 40599023, 2025). "During sepsis, PINK1 knockout suppresses Parkin-dependent mitophagy while enhancing dynamin-related protein 1 (Drp1)-mediated mitochondrial fission, ultimately leading to dendritic cell dysfunction and exacerbated immunosuppression." (PMID 40766066, 2025). "Sepsis increased the protein expression of PINK1, Ser65 phospho PARKIN, full‐length PARKIN and BNIP3 in survivors, suggesting that mitophagy signalling pathways were activated in response to mitochondrial damage." (PMID 40817441, 2025). "Impaired PINK1/Parkin-mediated mitophagy renders apoptosis of DCs, resulting in sepsis-induced immunosuppression." (PMID 38816685, 2024). "In sepsis, the dysfunction of DCs was prevented by regulating the quality control of mitochondria through protein tyrosine phosphatase (PTEN)-induced putative kinase 1 (PINK1)-mediated mitophagy, as indicated by a report." (PMID 38816685, 2024). "In summary, results from the current study support the concept that the changes in mitochondrial PINK1 expression of DCs during sepsis parallel the changes in DC function." (PMID 36809929, 2023). "The ratio of DCs expressing MHC-II, CD86, and CD80, the mRNAs level of dendritic cells expressing TNF-α and IL-12, and the level of DC-mediated T-cell proliferation were all decreased, both in vivo and in vitro during sepsis, when PINK1 was knocked out." (PMID 36809929, 2023). "Previous studies have demonstrated that PINK1-Parkin-dependent mitophagy represents a beneficial role in immunoregulation after sepsis." (PMID 36809929, 2023). "We found that changes in mitochondrial PINK1 expression of DCs paralleled changes in DC function during sepsis." (PMID 36809929, 2023). "Our results indicated that PINK1 protected against DC dysfunction during sepsis through the regulation of mitochondrial quality control, which suggested that PINK1 is a new therapeutic strategy for sepsis." (PMID 36809929, 2023). "Our results indicated that PINK1 protected against DC dysfunction during sepsis through the regulation of mitochondrial quality control." (PMID 36809929, 2023). "Mitophagy and mitochondrial dynamics are the processes of mitochondrial quality control, and therefore, we conclude that PINK1 protected against DC dysfunction during sepsis through the regulation of mitochondrial quality control." (PMID 36809929, 2023).
Sepsis (continued). "The restoration of mitochondrial Ca2+ in models with an overexpression of NCLX or PINK1 has been shown to be protective for PINK1-deficient neurons, LRRK2, and cardiomyocytes in sepsis." (PMID 35203354, 2022). "Nevertheless, our data support PINK1 as a therapeutic target to protect cardiomyocyte mitochondria, and the application of huMSC-exo is a promising strategy to combat sepsis-induced heart dysfunction." (PMID 33957982, 2021). "We confirmed the effect of the PINK1-PKA-NCLX axis on mitochondrial calcium homeostasis in cardiomyocytes during sepsis." (PMID 33957982, 2021). "It is recognized that the PINK1–parkin pathway triggers mitophagy and plays a major role in maintaining mitochondrial homeostasis during sepsis." (PMID 34257519, 2021). "In conclusion, we first confirmed that sepsis-induced PINK1-PKA-NCLX axis abnormalities in cardiomyocytes are the main cause of cardiomyocyte mitochondrial calcium overload and heart dysfunction." (PMID 33957982, 2021). "Participation of Pink1-Park2 pathway in maintenance of mitochondrial quality control via mitophagy has been widely studied, while a novel Pink1-Park2 protective neuro-immune pathway during sepsis was recently mentioned." (PMID 34824200, 2021). "Further research has found that in PINK1 or PARK2 knockout mice, sepsis increases more serious renal cell apoptosis and causes kidney injury." (PMID 34025411, 2021). "Our results highlight that the activation of PINK1/Parkin-mediated mitophagy to suppress pyroptosis via the Nrf2 pathway may serve as a potential therapeutic target for CDDO-Im in alleviating sepsis-induced ARDS." (PMID 40599023, 2025). "Notably, Gyp-XLIX counteracts sepsis-induced apoptosis and mitigates hyperactivation of the PINK1-Parkin mitophagy pathway, highlighting its capacity to restore mitochondrial homeostasis." (PMID 41026942, 2025). "Po-Ge-Jiu-Xin decoction (PGJXD) may alleviate sepsis-induced cardiomyopathy by modulating PINK1/Parkin-mediated mitophagy." (PMID 41148836, 2025). "Therefore, ISO-1 and T0467 were effective in mitigating sepsis-induced RTECs injury by activating the PINK1-Parkin pathway of mitophagy." (PMID 38956064, 2024). "Collectively, these results suggest that PINK1-Parkin-dependent mitophagy is induced during sepsis." (PMID 36809929, 2023). "Nevertheless, changes in PINK1 expression of DCs during sepsis and the effect of PINK1 on DC function are largely unknown." (PMID 36809929, 2023). "Collectively, we hypothesize that the changes in DC function may be related to the changes in mitochondrial PINK1 expression during sepsis." (PMID 36809929, 2023). "This suggested that PINK1 knockout prevented the function of DCs during sepsis." (PMID 36809929, 2023). "Therefore, in the current study, we used PINK1 knockout mice to explore the protective effects of PINK1 on DC function through regulating mitochondrial quality control during sepsis." (PMID 36809929, 2023). "In general, increased Beclin-1 signal in sepsis maintains the mass of functional mitochondria via selective facilitation of Pink1-Parkin mitophagy to eliminate dysfunctional mitochondria and promote mitochondrial biogenesis through Pink1/Parkin and AMPK/ULK1 pathways." (PMID 35706715, 2022). "Sepsis-AKI patients had lower mRNA expression of PTEN-induced putative kinase 1 (PINK1) and PARKIN, key components in regulating mitophagy and therefore important in the removal of unhealthy mitochondria, as compared to control subjects (p < 0.05 and p < 0.01, respectively)." (PMID 33494815, 2021). "Next, we explored the role of huMSCs-exo in heart protection during sepsis and whether PINK1-PKA-NCLX axis may be a therapeutic target." (PMID 33957982, 2021). "The functional importance of the PINK1-Parkin mitophagy pathway in regulating skeletal muscle mitochondrial function and quality in sepsis remains unknown." (PMID 32545383, 2020). "PGJXD may alleviate sepsis-induced cardiomyopathy by modulating PINK1/Parkin-mediated mitophagy." (PMID 41148836, 2025).
Sepsis (continued). "Finally, we determined the effect of PINK1 on DC apoptosis and mortality during sepsis." (PMID 36809929, 2023). "However, it has been unclear whether the expression of PINK1 is changed in DCs during sepsis and, if it changes, how PINK1 regulates DC function." (PMID 36809929, 2023). "Therefore, PINK1 may be a therapeutic target to protect cardiomyocyte mitochondria, and the application of huMSC-exo is a promising strategy against sepsis-induced heart dysfunction." (PMID 33957982, 2021). "Therefore, we hypothesized that the PINK1-PKA-NCLX axis in cardiomyocytes regulates mCa2+ efflux, similar to neurons, and abnormalities in this axis cause sepsis-induced mitochondrial calcium overload in cardiomyocytes." (PMID 33957982, 2021). "Sepsis survivors exhibited increased levels of PARKIN, PINK1 and BNIP3, suggesting impairment in both ubiquitin‐dependent and receptor‐mediated mitophagy pathways, but this was not thoroughly investigated." (PMID 40817441, 2025). "Puerarin and Torin1 can significantly inhibit the progression of sepsis by regulating mitochondrial autophagy-related proteins p62, LC3B, Pink1, and Parkin, thereby reversing lipopolysaccharide-induced suppression of mitochondrial autophagy in H9C2 cardiac cells." (PMID 40391374, 2025). "Compared with those in the Sham group, the expression levels of PINK1 and Parkin in the hippocampus of the CLP group were significantly greater, indicating that mitophagy in the hippocampus of the CLP group was increased during sepsis." (PMID 40016173, 2025). "Furthermore, PINK1 and PARK2 (parkin RBR E3 ubiquitin protein ligase) exhibit neuroimmunoprotective effects in sepsis." (PMID 40766066, 2025). "The activated form of Parkin (phospho-Ser65 Parkin) and Pink1 were not different between the groups (SPF vs. SF or Sepsis vs. SPF)." (PMID 37106730, 2023). "In our study, while the mitochondrial populations remained dysfunctional in the Sepsis mice, PINK1 and the Phospho-Ser65 Parkin did not increase, suggesting that PINK1-Parkin-dependent mitophagy was not activated." (PMID 37106730, 2023). "While the energy debt increased Bnip3 3.4-fold in the SPF mice, the Sepsis animals did not attain this level, suggesting an impairment in the PINK1-Parkin-independent mitophagy." (PMID 37106730, 2023). "The impact of alteration in the expression levels of Pink1/Parkin has been studied in LALI and demonstrate that these proteins, due to their role as homeostatic regulators of mitophagy, are necessary to respond in sepsis." (PMID 35431986, 2022). "However, since PINK1 and PARKIN mediate degradation of MFN2 and activation of DRP1 to prevent fusion while promoting fission, we cannot conclude that protein levels or activity of PINK1 and PARKIN and hence fusion/fission are unaltered in sepsis." (PMID 33494815, 2021). "In the absence of PINK1, there is a suppression of Ca2+ transients in the hippocampus, leading to elevated intracellular Ca2+ levels, which exacerbate sepsis-induced cognitive dysfunction in mice, highlighting the vital role of PINK1 in maintaining neuronal stability." (PMID 40823184, 2025). "By tailoring interventions to specific molecular nodes—whether enhancing PINK1-Parkin flux in fibrosis, restoring SIRT3 activity in sepsis, or targeting FUNDC1 in hypoxia—researchers are pioneering strategies to break the cycle of mitochondrial dysfunction and inflammation." (PMID 41026942, 2025). "In the current study, we investigated whether overexpressing Parkin, a key component of the PINK1-Parkin mitophagy pathway, could attenuate the negative impact of sepsis on skeletal muscles and their mitochondria." (PMID 32545383, 2020). "The present study examined the mechanism of cardiomyocyte mitochondrial calcium overload during sepsis and investigated whether MSC-exos protected heart function during sepsis by reducing mitochondrial damage and whether MSC-exos repaired mitochondrial damage via PINK1 and NCLX." (PMID 33957982, 2021).
Sepsis (continued). "When Pink1 mRNA contained in huMSC-exo was inhibited, huMSC-exo lost the ability of mCa2+ efflux regulation, and the PKA activity of recipient cardiomyocytes was not change in sepsis mouse hearts." (PMID 33957982, 2021).
colorectal cancer (31 papers, 2011 to 2026). A primary or metastatic malignant neoplasm that affects the colon or rectum. "We also identified the transcription and protein levels of the mitophagy genes such as PINK1 or Parkin as potential molecular markers for predicting ferroptosis sensitivity in colorectal cancer organoids and multiple cancer cell lines." (PMID 39679775, 2025). "SIRT3 is highly expressed in colorectal cancer cells with mitochondrial dysfunction, leading to PINK1/parkin-mediated mitophagy." (PMID 40134432, 2025). "Inhibition of mitophagy (PINK1/Parkin pathway), disrupting mitochondrial quality control, leading to ROS accumulation and promoting apoptosis in colorectal cancer cells." (PMID 41170235, 2025). "PTEN-induced kinase 1 (PINK1) orchestrates mitophagy and ferritinophagy, ensuring intracellular iron homeostasis crucial for the survival and growth of colorectal cancer cells." (PMID 38339263, 2024). "In summary, PINK1 is a tumor suppressor that modulates cellular metabolism and promotes colorectal cancer cell death." (PMID 36830954, 2023). "Another interaction partner is PINK1 and its interaction with PINK1 promoted the proteasome-mediated degradation of PINK1, which leads to the inhibition of mitophagy and apoptosis of colorectal cancer cells." (PMID 38060527, 2023). "Overall, the present study suggests that in SW480 and SW620 colorectal cancer cells, the apoptosis induced by dietary δVB involves PINK1/Parkin dependent-mitophagy." (PMID 34360883, 2021). "The aim of this study was to determine, via in silico methods, miRNA’s importance in BECN1, LAMP2, and PINK1 regulation and their possible role in the epigenetic changes in colorectal cancer." (PMID 33322704, 2020). "The study aimed to find those microRNAs (miRNAs) important in BECN1, LAMP2, and PINK1 regulation and to determine the possible role of the epigenetic changes in examined colorectal cancer using an in silico approach." (PMID 33322704, 2020). "However, we previously reported significantly higher levels of PINK1 immunoexpression in liver metastases from colorectal carcinomas compared to primary tumors of the colon." (PMID 40243539, 2025). "Expression of PINK1, miR-124, and miR-506 showed high impact probability in colorectal cancer." (PMID 39276929, 2024). "Previous researches uncovered that PINK1 and Parkin decreased in colorectal cancer." (PMID 37700273, 2023). "A downregulation of both PINK1 and Parkin have been observed in colorectal cancer patients." (PMID 34360883, 2021). "However, PINK1 played a detrimental role in colorectal cancer, and the role of PINK1 in ovarian cancer was controversial." (PMID 33244455, 2020). "MMR-deficient colorectal cancer cells were also reported to be preferentially sensitive to inhibitors of cytosine-based nucleoside analogs such as cytarabine, the PI3 kinase/AKT pathway, and the PTEN-induced putative kinase PINK1." (PMID 24205301, 2013). "The two single-nucleotide variants of PINK1 gene may be biomarkers of non-recurrence in colorectal cancer patients who received postoperative adjuvant chemotherapy." (PMID 37784019, 2023). "However, PINK1 played a detrimental role in colorectal cancer (DFS: Cox P = 0.001134)." (PMID 33244455, 2020). "Given that BNIP3L/NIX-dependent mitophagy is induced in colorectal cancer stem cells in response to DXR, it is likely that the pathway mediated by PINK1 and Parkin is the one mainly induced by DXR in BC cells." (PMID 38514650, 2024).